ENSG00000267261 (novel protein)
Gene: Protein-coding gene on chromosome 17 (42,119,674 to 42,154,916, reverse strand). Ensembl gene ENSG00000267261.
Genetic constraint (gnomAD): Loss-of-function variants: 12 observed, 30.25 expected, observed/expected ratio (o/e) 0.4, 90% interval 0.25 to 0.64. Missense variants: 221 observed, 353.57 expected, observed/expected ratio (o/e) 0.63, 90% interval 0.56 to 0.7. Synonymous variants: 129 observed, 137.52 expected, observed/expected ratio (o/e) 0.94, 90% interval 0.81 to 1.09.